SRP19 (signal recognition particle 19)
Description:
Component of the signal recognition particle (SRP) complex, a ribonucleoprotein complex that mediates the cotranslational targeting of secretory and membrane proteins to the endoplasmic reticulum (ER) (By similarity). Binds directly to 7SL RNA (By similarity). Mediates binding of SRP54 to the SRP complex (By similarity).
Tractability: Small molecule: a structure with a bound ligand is known; it has a binding pocket of medium quality. PROTAC: ubiquitination databases record sites on it; its protein half-life has been measured.
Gene: Protein-coding gene on chromosome 5 (112,861,188 to 112,898,371, forward strand). Ensembl gene ENSG00000153037.
Subcellular location: Cytoplasm; Nucleus, nucleolus; Nucleus, nucleoplasm
Subcellular location (Human Protein Atlas): Cytosol; Nuclear bodies
Pathways (Reactome):
Metabolism of proteins: SRP-dependent cotranslational protein targeting to membrane
Gene Ontology:
Molecular function: 7S RNA binding; protein binding; ribosome binding; RNA binding
Biological process: cotranslational protein targeting to membrane; SRP-dependent cotranslational protein targeting to membrane, signal sequence recognition; SRP-dependent cotranslational protein targeting to membrane
Cellular component: cytoplasm; cytosol; nucleolus; signal recognition particle; signal recognition particle, endoplasmic reticulum targeting; nucleoplasm
Genetic constraint (gnomAD): Loss-of-function variants: 11 observed, 23.12 expected, observed/expected ratio (o/e) 0.48, 90% interval 0.3 to 0.79. The upper end of that interval is the gene's LOEUF score, 0.79, which puts it in group 3 of 6, group 1 being the genes least tolerant of losing a copy. Missense variants: 168 observed, 183.4 expected, observed/expected ratio (o/e) 0.92, 90% interval 0.81 to 1.04. Synonymous variants: 61 observed, 60.38 expected, observed/expected ratio (o/e) 1.01, 90% interval 0.82 to 1.25.
Homologues: Orthologues: chimpanzee SRP19 (100% identical), dog SRP19 (99% identical), pig SRP19 (99% identical), mouse Srp19 (97% identical), rat Srp19 (97% identical), rabbit SRP19 (94% identical), guinea pig SRP19 (74% identical), zebrafish srp19 (70% identical), tropical clawed frog srp19 (68% identical), Drosophila melanogaster Srp19 (50% identical), Caenorhabditis elegans F37F2.2 (45% identical).
Diseases named in the same sentence as SRP19 in open-access papers:
SRP19 is named in the same sentence as 7 diseases in open-access papers, as found by Europe PMC text mining. Sharing a sentence is not in itself a finding about the gene and the disease. The quoted sentences say what the papers report.
colon cancer (1 paper, 2021). "SRP19 mRNA and protein levels were lowered in cell lines harboring APC deletion and shRNA targeting SRP19 inhibited proliferation of cells, confirming Srp19 as a CYCLOPOS gene in colon cancer with APC loss." (PMID 34113652, 2021). "Regulation of the expression of SRP genes and proteins in liver and colon cancer remains to be elucidated; however, alterations in the expression levels of SRP9/14 and SRP19 indicate a key role for SRP in gastro-related cancer." (PMID 34113652, 2021).
gastric cancer (1 paper, 2021). A primary or metastatic malignant neoplasm involving the stomach. "Srp19 gene has been associated with gastric cancer, with a significantly lower copy number compared to healthy patients and may serve as a potential novel biomarker to identify high-risk individuals." (PMID 34113652, 2021).
renal carcinoma (1 paper, 2025). A carcinoma arising from the epithelium of the renal parenchyma or the renal pelvis.
cancer (1 paper, 2019). A tumor composed of atypical neoplastic, often pleomorphic cells that invade other tissues. "The second network contained 6 of the identified autoantigens (AGO1, CSNK1G1, IFIT5, PHC3, SRP19, and UBE2S) out of the 35 molecules associated with cancer, organismal injury and abnormalities." (PMID 31494269, 2019).
SRP19 also shares sentences with these, for which no sentence is quoted: breast carcinoma (2 papers); brain cancer (1); colorectal cancer (1).